RNU6-182P (RNA, U6 small nuclear 182, pseudogene)
Gene: Small nuclear RNA gene on chromosome 2 (171,856,566 to 171,856,670, reverse strand). Ensembl gene ENSG00000252779.
Homologues: Orthologues: chimpanzee U6 (99% identical), macaque U6 (78% identical), dog U6 (70% identical), rabbit U6 (68% identical), mouse Gm25792 (62% identical), guinea pig U6 (61% identical), rat LOC120103222 (58% identical). Paralogues in human: RNU6-116P (75% identical), RNU6-959P (75% identical), RNU6-329P (74% identical), RNU6-1145P (73% identical), RNU6-1201P (73% identical), RNU6-1227P (73% identical), RNU6-310P (73% identical), RNU6-338P (73% identical), RNU6-38P (73% identical), RNU6-47P (73% identical), RNU6-48P (73% identical), RNU6-698P (73% identical), and 1286 more.